MIR1302-2 (microRNA 1302-2)
Synonyms: hsa-mir-1302-2; MIRN1302-2
Gene: MicroRNA gene on chromosome 1 (30,366 to 30,503, forward strand). Ensembl gene ENSG00000284332.
Gene Ontology:
Biological process: miRNA-mediated post-transcriptional gene silencing
Homologues: Paralogues in human: MIR1302-10 (100% identical), MIR1302-11 (100% identical), MIR1302-9 (100% identical).